CXCR5 (C-X-C motif chemokine receptor 5)
Description:
Cytokine receptor that binds to B-lymphocyte chemoattractant (BLC). Involved in B-cell migration into B-cell follicles of spleen and Peyer patches but not into those of mesenteric or peripheral lymph nodes. May have a regulatory function in Burkitt lymphoma (BL) lymphomagenesis and/or B-cell differentiation.
Synonyms: CD185; BLR1; MDR15
Tractability: Small molecule: it belongs to a druggable protein family. Antibody: its Gene Ontology location is reachable by antibodies, with high confidence; UniProt places it where antibodies can reach, with medium confidence; UniProt predicts a signal peptide or a membrane-spanning region. PROTAC: ubiquitination databases record sites on it; its protein half-life has been measured; a small molecule that binds it is known.
Target class: Peptide receptor (family A GPCR); Membrane receptor; Family A G protein-coupled receptor; CXC chemokine receptor; Chemokine receptor
Gene: Protein-coding gene on chromosome 11 (118,883,892 to 118,897,787, forward strand). Ensembl gene ENSG00000160683.
Subcellular location: Cell membrane
Pathways (Reactome):
Signal Transduction: Chemokine receptors bind chemokines; G alpha (i) signalling events
Gene Ontology:
Molecular function: protein binding; C-C chemokine binding; C-C chemokine receptor activity; G protein-coupled receptor activity; C-X-C chemokine receptor activity
Biological process: positive regulation of cytokinesis; calcium-mediated signaling; cell chemotaxis; G protein-coupled receptor signaling pathway; immune response; positive regulation of cytosolic calcium ion concentration; B cell activation; chemokine-mediated signaling pathway; chemotaxis; lymph node development
Cellular component: external side of plasma membrane; plasma membrane; membrane
Genetic constraint (gnomAD): Loss-of-function variants: 3 observed, 5.96 expected, observed/expected ratio (o/e) 0.5, 90% interval 0.23 to 1.29. That is too few expected variants to judge how well the gene tolerates losing a copy. Missense variants: 333 observed, 507.28 expected, observed/expected ratio (o/e) 0.66, 90% interval 0.6 to 0.72. Synonymous variants: 218 observed, 226.32 expected, observed/expected ratio (o/e) 0.96, 90% interval 0.86 to 1.08.
Homologues: Orthologues: chimpanzee CXCR5 (99% identical), macaque CXCR5 (97% identical), guinea pig CXCR5 (88% identical), rabbit CXCR5 (87% identical), dog CXCR5 (86% identical), mouse Cxcr5 (83% identical), pig CXCR5 (82% identical), rat Cxcr5 (82% identical), tropical clawed frog cxcr5 (42% identical), zebrafish cxcr5 (36% identical). Paralogues in human: CXCR3 (37% identical), CXCR2 (35% identical), CCR7 (32% identical), CXCR1 (31% identical), CCR10 (29% identical), CCR4 (29% identical), CXCR4 (29% identical), CCR6 (28% identical), CCR9 (28% identical), ACKR2 (27% identical), CCR1 (27% identical), CCR3 (27% identical), and 11 more.
Diseases named in the same sentence as CXCR5 in open-access papers:
CXCR5 is named in the same sentence as 284 diseases in open-access papers, as found by Europe PMC text mining. Sharing a sentence is not in itself a finding about the gene and the disease. The quoted sentences say what the papers report.
autoimmune disease (52 papers, 2008 to 2025). A disorder resulting from loss of function or tissue destruction of an organ or multiple organs, arising from humoral or cellular immune responses of the individual to their own tissue constituents. "Overexpression of CXCR5 on B cells leads to overactivation of B cells and then causes antibody-mediated autoimmune diseases." (PMID 36685576, 2022). "In this review, we provide a comprehensive overview of the pathogenic role of CXCL13/CXCR5 axis in autoimmune diseases, while also discussing the potential usage of CXCL13 as a novel clinical biomarker and treatment target." (PMID 35309354, 2022). "The expression of CXCR5 on TFH cells is associated with autoimmune disease progression and serum levels of CXCR5 on TFH cells are associated with aggravated rheumatoid arthritis." (PMID 35624463, 2022). "We also detected elevated levels of chemokine CXCL13 and its receptor CXCR5 which involve the maintenance of pathogenic B cells in autoimmune diseases like MS." (PMID 29503661, 2018). "Recent studies have found that CXCL13 and its receptor CXCR5 are implicated in the pathogenesis of several autoimmune diseases, such as rheumatoid arthritis, multiple sclerosis, systemic lupus erythematosus, primary Sjögren’s syndrome, myasthenia gravis, and inflammatory bowel disease." (PMID 35309354, 2022). "As the sole known ligand for CXCR5, which is expressed on mature B cells and Tfh cells, aberrant CXCL13 expression of CXCL13 in ectopic germinal centers has been implicated in various autoimmune diseases." (PMID 41567208, 2025). "Altered expression levels of T cell immunoglobulin and mucin-domain containing-3 (TIM-3), C-X-C chemokine receptor type 5 (CXCR5), and programmed cell death protein 1 (PD-1) are implicated in the progression of inflammatory and autoimmune diseases." (PMID 38426098, 2024). "A large body of evidence suggests that in the development of autoimmune diseases, the activation of Th0 cells or the downregulation of Tfh cells’ CXCR5 expression in peripheral blood cells leads to the generation of Tph cells." (PMID 39390361, 2024). "In additional, there are many reports of CD20-expressing T cells (or CD20 + T cells) and CXCR5+ CD8 T cells on autoimmune diseases, especially on MS and RA." (PMID 38378668, 2024). "There are many reports of CD20-expressing T (or CD20 + T) and CXCR5+ CD8 T cells on autoimmune diseases, especially on multiple sclerosis and rheumatoid arthritis." (PMID 38378668, 2024). "CXCL13 is the only ligand for CXCR5 and the CXCL13/CXCR5 axis is associated with the development of tumors, autoimmune diseases, infectious diseases, and many other diseases." (PMID 37382265, 2023). "In the past decade research has focused on elucidating the regulation and functionality of CXCR5+ T follicular cells (Tfh) during infection, cancer, and autoimmune disease." (PMID 36314014, 2022). "This review highlights the biological functions, protein structures, signaling transduction pathways, and roles of CXCL13/CXCR5 in the pathogenesis of autoimmune diseases." (PMID 35309354, 2022). "In brief, although numerous challenges remain, CXCL13/CXCR5 axis is undoubtedly a promising therapeutic target for human autoimmune diseases." (PMID 35309354, 2022). "The pivotal role CXCL13/CXCR5 axis in ELSs development has been detected in several autoimmune diseases such as RA and pSS." (PMID 35309354, 2022). "In animal models of autoimmune diseases, knockout or neutralization of CXCL13/CXCR5 significantly improve clinical symptoms, suggesting that CXCL13/CXCR5 can be used as a therapeutic target for autoimmune diseases." (PMID 35309354, 2022). "In this review, we discuss the biological features of CXCL13 and CXCR5 and the recent findings on the pathogenic roles of the CXCL13/CXCR5 axis in autoimmune diseases." (PMID 35309354, 2022). "Inhibiting the CXCL13/CXCR5-mediated signaling pathway is a new direction for the treatment of autoimmune disorders." (PMID 34518512, 2021).
autoimmune disease (continued). "Whereas, the CXCL13:CXCR5 axis has been best characterized in these autoimmune disorders through the aberrant activity and differentiation of B-cells, numerous other autoimmune conditions appear to be driven by T follicular helper cells TFH cells." (PMID 31354634, 2019). "This all is in line with the fact that fully developed eLFs with FDCs, compartmentation into a light and dark zone, an excess of GC-B cells over TFHs as well as the presence of “true”, i.e., active CD4+CXCR5+BCL-6+ TFHs are rare in human autoimmune diseases." (PMID 32010141, 2019). "The mechanisms by which CD8 T cells mediate autoimmune disease pathology remain largely unresolved, but inflammation and autoimmune disease studies suggest a helper function for CXCR5+ CD8 T cells." (PMID 31275308, 2019). "Although yet untested, CXCR5+ CD8 T cell function in autoimmune disease likely includes canonical cytotoxic mechanisms in addition to acquired Tfh mechanisms." (PMID 31275308, 2019). "In the context of chronic inflammation and autoimmune disease, CXCR5+ CD8 T cells likely employ diverse mechanisms to promote inflammatory responses and advance disease pathogenesis at the site of autoreactive responses within ectopic GCs or lymphoid tissue." (PMID 31275308, 2019). "IFNγ is a known mediator of B class-switch to IgG2a/c, yet CXCR5+ CD8 T cells that arise in spontaneous autoimmune disease induced B cell class-switch to predominately IgG1." (PMID 31275308, 2019). "On the contrary, ICOS overexpression induces overproduction of CXCR5+CD4+TFH cells and causes exuberant GC responses and remarkably promotes antibody production with autoimmune disease in mice." (PMID 26491701, 2015). "We discovered notable variations in CXCR5 DNA methylation levels across patients with RA and SLE compared with HC, indicating that CXCR5 methylation status may contribute to the pathophysiology of these autoimmune disorders." (PMID 39835879, 2025). "ICB induced reactivation of exhausted CXCR5+ T cells during autoimmunity may enable new autoimmune disease therapies." (PMID 36314014, 2022). "Expression levels and effects of CXCL13/CXCR5 axis in autoimmune diseases." (PMID 35309354, 2022). "Besides, CXCL13/CXCR5 axis plays similar roles in other autoimmune diseases, such as MS, SLE, MG, and so on." (PMID 35309354, 2022). "Indeed, numerous preclinical studies support the concept of suppressing the CXCL13/CXCR5 axis as a novel therapeutic approach for autoimmune diseases treatment." (PMID 35309354, 2022). "Interestingly, recent reports have focused on the role of CXCL13 and its receptor “CXCR5” as a B-cell chemoattractant, especially in autoimmune diseases." (PMID 35457267, 2022). "In autoimmune disease, CXCR5+CD8 T cells enable B cell differentiation and exacerbate disease." (PMID 36314014, 2022). "Due to its essential role in immune regulation and inflammatory response, CXCL13/CXCR5 axis may serve as a potential therapeutic target for autoimmune diseases." (PMID 35309354, 2022). "However, there has been only limited research on the function of CXCL13/CXCR5 axis in these autoimmune diseases, and more studies are required to provide further insights." (PMID 35309354, 2022). "Therapeutic effects on targeting CXCL13/CXCR5 axis in autoimmune diseases." (PMID 35309354, 2022). "To summarize, these results suggest that the CXCL13/CXCR5 axis is a promising target for autoimmune diseases, which may open avenues for novel strategies for autoimmune diseases treatment." (PMID 35309354, 2022). "Beyond the field of cancer therapies, CXCR5 targeting could also be applied for the treatment of autoimmune diseases; we expect selective depletion of mature B cells and of Tfh cells that can promote autoimmunity without impact on precursor B cells." (PMID 33431832, 2021). "Interestingly, therapeutic agents targeting CXCL13/CXCR5 are currently being explored in the context of autoimmune disease and non-Hodgkin lymphoma." (PMID 34615710, 2021).
autoimmune disease (continued). "Over the last decade, aberrant responses of T follicular helper (Tfh) cells, a subset of CD4 T cells which are able to localise predominantly in the B cell follicles through a high level of chemokine receptor CXCR5 expression, are described in pathogenesis of several autoimmune diseases." (PMID 34461933, 2021). "Moreover, the interaction of CXCL13 with its specific receptor CXCR5 enhances B-cell maturation and the synthesis of antibodies in autoimmune diseases." (PMID 34518512, 2021). "Taken together, anti-CXCR5 CAR-T cells do not only provide a superior treatment strategy for B-NHL by co-targeting Tfh cells of the TME but also have the capacity to eliminate autoreactive B cells for the treatment of autoimmune diseases." (PMID 33431832, 2021). "Similarly, in the context of autoimmune disease, CXCR5+ CD8 T cells largely lack ICOSL, FoxP3, and Helios expression (unpublished data)." (PMID 31275308, 2019). "Recently, it has been addressed that CXCR5+CD4+ T cells are detected in organs that are affected by autoimmune disorders, such as systemic lupus erythematosus and Sjogren’s syndrome, suggesting that aberrant Tfh cells may induce autoimmunity." (PMID 29709026, 2018). "Alterations in the cTfh compartment have been found in several ab-mediated autoimmune diseases, like SLE and RA, in which the expansion of cTfh cells (defined as CD4+CXCR5+PD-1+ICOS+ T cells) could be linked to disease activity." (PMID 26872212, 2016). "CXCL13 and CXCR5 are in fact involved in normal lymphocyte trafficking and homing in secondary lymphoid organs and are highly expressed in various autoimmune diseases characterized by the occurrence of ectopic lymphoid follicles, which are also a prominent feature of AIPC." (PMID 18596913, 2008). "However, in the context of autoimmune diseases, CXCR5‐mediated cell localization may lead to abnormal antibody production, attacks on self‐tissue, or excessive inflammatory responses, thereby promoting disease development and persistence." (PMID 39835879, 2025). "In addition, the CXCL13/CXCR5 axis may also have disease-specific pathogenetic mechanisms in certain autoimmune diseases, which will be discussed further below." (PMID 35309354, 2022). "This brings us to CXCL13 as a soluble part of the CXCL13/CXCR5 immune axis, which is, as is the case for cTfh cells, physiologically detectable in blood and increased upon immune activation in the same contexts of infection, vaccination, and autoimmune disorders." (PMID 36078057, 2022). "In addition, recent studies have revealed that CXCL13/CXCR5 may also have a disease-specific pathological mechanism in some autoimmune diseases." (PMID 35309354, 2022). "We also detect and characterize tertiary lymphoid structures marked by CXCL13/CXCR5 and CCL19-mediated signaling from Tph cells and immunoregulatory DCs, analogous to those observed in other autoimmune diseases." (PMID 41269758, 2025). "Antibody-suppressor cells, namely CXCR5+PD-1−CD8 T cells, may activate effector functions on self-reactive B cells and CD4 Tfh cells leading to tolerance and inhibition of plasma cell formation thus halting autoantibody production associated with many autoimmune diseases." (PMID 36314014, 2022). "CXCR5 and its ligand CXCL13 are involved in chronic inflammation, infectious and immune responses, and autoimmune disorders." (PMID 34947816, 2021). "Chemokine receptors CCR5, CCR9, CCR10, CXCR2, CXCR4, CXCR5 and CXCR7 are also involved in various cancers initiation and metastasis, autoimmune diseases, viral infections and cytokine release syndrome, also called “cytokine storm”." (PMID 34947816, 2021). "Ectopic germinal center-like lymphoid structures have been recognized within the affected tissues in numerous autoimmune diseases, including myasthenia gravis and rheumatoid arthritis, long before the cloning of CXCL13 and CXCR5." (PMID 31354634, 2019).
autoimmune disease (continued). "Overall, dysregulation of the CXCL13:CXCR5 axis affecting both B- and TFH cell function is major player in autoimmune disorders, and potentially serves as a biomarker for disease progression and therapeutic response." (PMID 31354634, 2019). "CXCR5+ CD8 T cells control viral load during infection, and also promote antibody-mediated autoimmune disease progression." (PMID 31275308, 2019). "Although the incidence of autoimmune diseases in patients with chronic hepatitis B was not investigated in this research, it could be presumed that the autoimmune manifestations might be associated with the augmented function of blood CXCR5+CD4+ T cells." (PMID 27612199, 2016). "Of particular interest in this respect are the recently described CXCR5-negative human peripheral helper T cells which have first been shown to expand in autoimmune diseases." (PMID 35237272, 2022). "Notably, PD1+ CXCR5+ CD8 T cells in chronic viral infection and progenitor exhausted CD8 T cells from the tumors as well as CD27+ Th17 cells from autoimmune disease display stemness." (PMID 33370392, 2020). "Several studies demonstrated that the frequency of CXCR5+CD4+ T cells was not significantly increased in patients with autoimmune diseases, such as SLE, autoimmune thyroid disease, and juvenile dermatomyositis, compared to healthy controls." (PMID 24655429, 2014). "Circulating Tfh (cTfh) cells, contain long-lived memory cells characterized by CD4+CXCR5+CD45RA- in peripheral blood, are functionally similar to GC Tfh cells, can induce autoantibody production by B cells, and play an important role in the pathogenesis of autoimmune diseases including SLE." (PMID 36119056, 2022). "However, when pathological conditions such as autoimmune diseases occur, Tfh cells undergo pathological activation and amplification, including abnormal expression of molecules such as CXCR5, and migration to nonlymphoid tissues of the body to form lymphoid tissues containing ectopic GC." (PMID 32416035, 2020). "Furthermore, CXCL13/CXCR5-associated immune activities occur in non-lymphoid tissues, where they contribute to organizing and shaping in situ adaptive immune responses via the formation of ELS at chronic inflammatory sites during persistent infections, autoimmune diseases, and cancer." (PMID 36078057, 2022).